IL27RA (interleukin 27 receptor subunit alpha)
Diseases named in the same sentence as IL27RA in open-access papers (continued):
Sharing a sentence is not in itself a finding about the gene and the disease.
infection (continued). "However, later studies confirmed that IL-27Rα−/− mice developed normal Th1 response after infection, and IL-27 could induce IL-10 and SOCS3 to suppress Th1 cells, suggesting the bidirectional role of IL-27 in Th1 cells." (PMID 34299138, 2021). "(A) WT and Il27ra–/– were infected, treated with 5 mg BRDU, and kept on 1 mg/ml BRDU in the drinking water throughout infection." (PMID 41396163, 2025). "Fourteen days post-infection, the body weight changes and BLI values were similar between IL-27Rα−/− mice treated with rAAV-IL-27p28 and those treated with rAAV-GFP." (PMID 36028492, 2022). "C57BL/6 (WT) and IL-27Rα−/− mice were challenged with bioluminescent MRSA (USA300 LAC::lux), and tibiae were harvested 14 days post-infection to assess the bacterial load and measure IL-27 levels via ELISA." (PMID 36028492, 2022). "IL-27Rα−/− CD4 T cells were more glycolytic, suggesting that IL-27 seems to limit Th1 cell glycolysis to further protect against tissue pathology during infection." (PMID 34045653, 2021). "WT levels of TNF-α, IL-1, and IL-6 increased robustly in WT pups following infection, while TNF-α and IL-6 expression was significantly reduced in IL-27Rα−/− pups." (PMID 31818960, 2020). "When infected with T. gondii, these mice phenocopied whole body Il27ra–/– mice and developed lethal immune pathology >10 days post-infection (data not shown)." (PMID 41396163, 2025). "Although IL-27 can promote T cell responses, mice lacking IL-27Rα or sub-units have stronger T cell responses in various infection models." (PMID 39679172, 2024). "It is notable that in this report, IL-10 was among the genes that failed to increase during infection in the spleen of IL-27Rα-/- pups." (PMID 36891292, 2023). "That genes in these same pathways are not increased in IL-27Rα KO neonatal pups during infection is the most compelling finding in this report." (PMID 36891292, 2023). "The change in global gene expression with IL27Rα depletion compared to WT in the absence of infection is not dramatic and reveals only a limited number of differentially expressed genes." (PMID 36891292, 2023). "IL-27Rα−/− mice lost significantly more weight than WT mice by day 6 post-infection (data not shown)." (PMID 25651926, 2015). "Gene expression analysis demonstrated a strong upregulation of IL23A (encodes p19) by infection, whereas IL23R, Epstein–Barr virus-induced gene 3 (EBI3), IL6ST, IL12A, and IL27RA were found to be expressed, but not regulated, or to a lesser extent." (PMID 24069393, 2013). "Similarly, at the 48 hour timepoint, pattern "MTB" includes 288 genes whose expression levels changed preferentially after infection with mycobacteria (e.g. CCL1, ATP6V1A, IL27RA), but only 33 of these genes are in the corresponding pattern at the 18 hour timepoint." (PMID 26586179, 2015). "Published data shows that a cell-extrinsic increase in KLRG1 is unlikely to be secondary to reduced IL-10 production in Il27ra-/- mice, as Il10-/- and Il10r-/- mice show no (or a very marginal) upregulation of KLRG1 upon infection." (PMID 30044874, 2018).
tumor (35 papers, 2011 to 2026). "On the other hand, IL-27Rα expression in different tumor cell lines is associated with the inhibition of effector responses and the promotion of tumor growth." (PMID 38607023, 2024). "IL-27p28, the ligand for IL27RA, has been linked with tumor progression, self-renewal and tumorigenicity, expression of inflammatory mediators, tumor immune invasion and regulated chemokine axis via STAT1/STAT3 signaling." (PMID 31628349, 2019). "In this study, we demonstrate that tumor development and growth are accelerated in IL-27 receptor α (Il27ra)-deficient mice." (PMID 23554861, 2013). "Notably, IL-27Fc-dependent tumor control was abrogated in mice with CTL-restricted IL-27RA deficiency." (PMID 40254608, 2025). "Further multivariate analysis unveiled significant insights: LRP1, PAEP, PI3, OBP2A, and IL27RA genes exhibited higher levels in the tumour group, whereas FOS, PDGFRA, and FGF7 showed higher expression in normal ovarian tissue (all p < 0.001)." (PMID 39063239, 2024). "Another was a ‘cancer-cell’ model, where tumor cell lines were selected that expressed variable levels of IL-27Rα." (PMID 35200430, 2022). "In conclusion, the overall reduction in immune cell infiltrates made it unlikely that specific lymphocyte subsets account for the altered tumor growth in IL27Rα KO mice." (PMID 31637217, 2019). "Within the bulk tumor mRNA, we detected a trend toward higher expression of M2-like macrophage markers in tumors of IL27Rα KO mice at early and late tumor stages." (PMID 31637217, 2019). "There was a tendency toward decreased proliferation of tumors growing in IL27Rα KO mice, and a major increase in apoptotic tumor cells in IL27Rα KO compared to WT mice, both in early and late-stage tumors." (PMID 31637217, 2019). "Correlating with reduced tumor growth, we also observed a lower number of pulmonary metastasis in IL27Rα KO mice with 31 days old tumors." (PMID 31637217, 2019). "In WT mice, BSA-FITC was mainly observed within tumor vessels, whereas in tumors of IL27Rα KO mice, FITC-BSA leaked into the tumor area surrounding vessels (arrows)." (PMID 31637217, 2019). "To better understand increased HIF1α expression and HIF-responses in tumors of IL27Rα KO mice, we analyzed the number and morphology of tumor blood vessels using immunofluorescence and multi-spectral FACS." (PMID 31637217, 2019). "Based on the intersection of interleukin receptor superfamily signature between human BC tissues and cell lines to exclude the tumor heterogeneity, IL27RA was predominantly expressed in both TNBC tissues and cell lines." (PMID 30728901, 2019). "To understand reduced tumor growth in IL27Rα KO mice, we next analyzed proliferation and apoptosis of tumor cells." (PMID 31637217, 2019). "The observation that mice are resistant to cutaneous skin carcinogenesis upon deletion of IL27RA in hematopoietic compartment suggests that most likely IL27 signaling through these cells is needed to promote tumor growth and angiogenesis." (PMID 27738312, 2016). "To examine the immunological effects of the loss of IL-27 signaling during the anti-tumor response, we isolated TDLN, NDLN and spleens from tumor bearing Il27ra+/+ and Il27ra−/− mice." (PMID 23554861, 2013). "Immunohistochemical analysis of FoxP3+ cells within MCA tumor tissues revealed an average 2-fold increased Treg numbers in Il27ra−/− compared to Il27ra+/+ mice." (PMID 23554861, 2013). "The moderate reduction in IFN-γ production by CD8+ cells in Il27ra−/− mice in tumor models is in contrast with infectious models, where a strong requirement for IL-27R signaling and T-bet induction was observed." (PMID 23554861, 2013). "Cytokine production by T cells from Il27ra+/+ and Il27ra−/− tumor bearing mice was assessed by flow cytometry." (PMID 23554861, 2013). "Tumor development occurred significantly earlier in Il27ra−/− mice, with median disease free survival of 11 weeks, compared with 16.5 weeks in Il27ra+/+ mice." (PMID 23554861, 2013).
tumor (continued). "Thus, ARPC1B, ELF3, VSTM2L, and IL27RA were identified as potential tumour antigens for mRNA vaccine production." (PMID 37779866, 2023). "Our further research suggested that WAKMAR2 is crucial in regulating the tumour microenvironment and may function by regulating immune-related genes, including IL27RA, RAC2, FABP7, IGLV1-51, IGHA1, and IGHD." (PMID 34321580, 2021). "Expression of the classical M1 marker Nos2 was significantly decreased in tumors of IL27Rα KO mice, which may suggest a reduced anti-tumor potential of TAM in tumors of IL27Rα KO mice." (PMID 31637217, 2019). "As tumors of IL27Rα KO mice were more hypoxic, an impaired oxygen supply may account for reduced growth and increased tumor cell death." (PMID 31637217, 2019). "In conclusion, we excluded macrophages as major players in reducing tumor growth in IL27Rα KO mice." (PMID 31637217, 2019). "Therefore, here we establish a direct positive correlation between tumor grade and the number IL27RA-positive stroma cells in the human skin SCC." (PMID 27738312, 2016). "In addition, significantly increased Treg cell percentages were observed in TDLN (day 28) and in the spleen of Il27ra−/− mice with PyMT tumor transplants, compared to Il27ra+/+ controls." (PMID 23554861, 2013). "To study whether this was linked to IL-27-signaling in macrophages, we generated BMDM from WT and IL27Rα KO mice and induced classical activation with LPS/IFNγ, alternative activation with IL-4, or directly co-cultured them with PyMT cells to induce tumor-like conditions." (PMID 31637217, 2019). "Moreover, tumor progression in IL27Rα KO mice was strongly reduced from day 21 onwards." (PMID 31637217, 2019). "Although not reaching statistical difference (P= 0.1224), a trend was observed the recipient mice seemed to also make a difference: wildtype recipient mice are more resistant to tumor formation than IL27RA−/− mice regardless whether they received bone marrow derived from wildtype or IL27RA−/− mice." (PMID 27738312, 2016). "LRP1, AKT2, PI3, IL27RA, OBP2A, and PAEP were found to be more expressed in OC tumour samples than in normal tissues." (PMID 39063239, 2024). "Based on transcription data from The Cancer Genome Atlas (TCGA), we identified four tumour-specific antigens for vaccine production: ARPC1B, ELF3, VSTM2L, and IL27RA." (PMID 37779866, 2023). "IL27RA is the alpha subunit of Interleukin 27 (IL27) receptor, which has been reported to demonstrate a dual role of anti-tumor activity and immune regulatory function." (PMID 31221207, 2019). "To investigate the selective effects of IL-1a and IL-27 on certain tumor cell lines, we quantified mRNA expression for the subunits of the IL-1a (IL1R1, IL1RAP) and IL-27 receptors (IL27RA, IL6ST)." (PMID 31730010, 2019). "Given the leakiness of vessels in tumors of IL27Rα KO mice, we analyzed expression of the pericyte marker neural/glial antigen 2 (NG2) in tumor sections." (PMID 31637217, 2019). "Interestingly, IL-27rα−/− mice treated with AOM and DSS had upregulated tumor load, tumor numbers, and tumor size, and increased percentage of myeloid-derived suppressor cells (MDSCs)." (PMID 38566992, 2024). "At protein level, we detected increased VEGF amounts in tumor supernatants of late stage tumors, but no changes between tumors growing in IL27Rα KO or WT mice." (PMID 31637217, 2019). "Since immune cells did not explain reduced tumor growth in IL27Rα KO mice, we focused on other stromal cells." (PMID 31637217, 2019). "To determine the effects of TTP-mediated IL-27 inhibition on tumor development, we employed a murine mammary gland tumor model by inoculating E0771 cells into mammary gland pads of WT, Zfp36−/−, IL27ra−/− and TTP/WSX-1 DKO mice, followed by monitoring of tumor growth." (PMID 29021521, 2017). "Tumor growth in animals lacking IL27Rα was markedly reduced." (PMID 31637217, 2019).
cancer (12 papers, 2011 to 2025). A tumor composed of atypical neoplastic, often pleomorphic cells that invade other tissues. "Although the role of IL-27RA in cancer is unknown, preclinical studies have shown that IL-27 inhibits tumor cell growth." (PMID 33804039, 2021). "In order to understand the significance and relevance of IL27 signaling in the bone marrow cells to human cancer patients, we analyzed the levels of IL27RA in normal vs. malignant tissue and determined the IL27RA-positive cells in the stroma in correlation to the disease progression." (PMID 27738312, 2016). "Eight genes were shared between all three cancer types (KIAA1949, IL-27RA, PSMB8, TRIM21, VAMP5, CASP4, TYMP, and STX4)." (PMID 33804039, 2021).
inflammation (3 papers, 2017 to 2024). Aberrant reaction of the microcirculation characterized by movement of fluid and leukocytes from the blood into extravascular tissues. "Furthermore, IL-27rα−/− and Treg-specific IL-27rα−/− mice were injected with cockroach antigen, showing severe airway inflammation, whereas IL-27 treatment showed little effects on reducing the inflammatory responses." (PMID 38566992, 2024). "Consequently, we concluded that Th17 cell-derived TGF-β1 regulates the stability of Th17 cells and inhibits the pathogenic conversion of Th17 cells into Th1-like exTh17 cells by regulating the expression of IL-12Rβ2 and IL-27Rα during CNS or intestinal inflammation in vivo." (PMID 34050263, 2021).
metabolic disease (2 papers, 2022 to 2025). A congenital disorder (due to inherited enzyme abnormality) or acquired (due to failure of a metabolically important organ) disorder resulting from an abnormal metabolic process. "The IL-27 receptor (IL-27Ra, or WSX-1) expresses on adipocytes and plays an important role in promoting metabolic diseases." (PMID 35963848, 2022).
IL27RA also shares sentences with these, for which no sentence is quoted: autoimmune disease (2 papers); experimental autoimmune encephalomyelitis (2); Hepatitis (2); hepatocellular carcinoma (2); pneumonia (2); tuberculosis (2); vasculitis (2); abscess (1); African trypanosomiasis (1); age-related macular degeneration (1); Anxiety (1); aortic aneurysm (1); autoinflammatory syndrome (1); bacterial infection (1); bacterial pneumonia (1); breast tumor (1); cardiomyopathy (1); Chagas disease (1); chlamydial infection (1); Chronic colitis (1); colon cancer (1); Crohn disease (1); emphysema (1); endometrial cancer (1); eosinophilia (1); glioma (1); glomerulonephritis (1); heart disease (1); hematological malignancies (1); hematopoietic neoplasms (1).
A further 37 diseases each share a sentence with IL27RA in 1 paper.